NCOA4 (nuclear receptor coactivator 4)
Diseases named in the same sentence as NCOA4 in open-access papers (continued):
Sharing a sentence is not in itself a finding about the gene and the disease.
neurodegenerative disease (10 papers, 2019 to 2025). A disorder of the central nervous system characterized by gradual and progressive loss of neural tissue and neurologic function. "Mounting evidence shows that the loss and dysfunction of NCOA4 potentially contribute to the inappropriate accumulation of ferritin and trigger excessive oxidative stress and cytotoxicity in neurodegenerative diseases and cardiovascular diseases." (PMID 33632938, 2021). "NCOA4 (nuclear receptor coactivator 4), a selective cargo receptor that mediates ferritinophagy and maintains iron homeostasis in cells and systems, is associated with neurodegenerative diseases." (PMID 37047371, 2023). "Given that NCOA4‐mediated ferritinophagy has been noticed to implicate in iron homeostasis and classical autophagic pathway, it is hypothesised that ferritinophagy deficiency might be the underlined mechanism for improper iron deposition in neurodegenerative diseases." (PMID 38389491, 2024). "The expression and function of NCOA4 in the brain and its role in neurodegenerative disease are unexplored areas of research, and it is necessary to further study its molecular mechanisms and signaling pathways." (PMID 39306799, 2024). "Recently, the central function of NCOA4‐mediated ferritinophagy in neurodegenerative diseases has attracted more attention, as evidenced by the high expression of NCOA4 in murine brain tissue at both mRNA and protein levels." (PMID 38389491, 2024). "In neuroscience, it has been found that NCOA4-mediated ferritinophagy plays an important role in neurodegenerative diseases." (PMID 38136217, 2023). "We propose additional studies to examine the potential role of NCOA4 in the brain in the context of neurodegenerative diseases." (PMID 30930742, 2019). "This reduction causes a decrease in oxidative stress levels and a corresponding decrease in sensitivity to iron‐dependent death, indicating that the inhibition of NCOA4 may have a protective effect on the brain in neurodegenerative diseases." (PMID 39306799, 2024). "However, the expression and function of NCOA4 in the central nervous system and its role in neurodegenerative diseases is an unexplored area of research." (PMID 33632938, 2021). "Consequently, it resulted in attenuated oxidative stress and lower sensitivity to ferroptotic cell death, indicating that downregulated NCOA4 could exert a protective impact on neurocytes in the setting of neurodegenerative diseases." (PMID 38389491, 2024). "Evidence shows that NCOA4 mRNA and protein are expressed in the brains of mice, but there is currently no research on the expression level or function of NCOA4 in pathological specimens of patients with aging or neurodegenerative diseases." (PMID 39306799, 2024).
bacterial infection (1 paper, 2022). "Here, western blotting showed that NCOA-4 protein expression increased in the RAW264.7 cells at 3-12 h after bacterial infection, then decreased at 24 h." (PMID 35265210, 2022). "Thus, both the Nrf-2/HO-1 and ferritin/NCOA-4 axes are activated in the early stage of bacterial infection in macrophages to increase ferrous iron to a high level." (PMID 35265210, 2022).
central nervous system diseases (1 paper, 2023). "Recently, evidence has surfaced of the identification of the vital role of NCOA4-mediated ferritinophagy in the pathogenesis of central nervous system diseases." (PMID 37950727, 2023).
neurological disorders (1 paper, 2023). "Functional network analyses of transcriptome data revealed neurological disease and nervous system development and function as part of the functional networks associated with NCOA4 deficiency." (PMID 36742433, 2023). "The transcriptomic and proteomic profiles of NCOA4 deficiency in HT22 cells revealed enrichment of gene responses functionally associated with neurobiology and neurological disorders, and their interaction with cellular iron status." (PMID 36742433, 2023).
NCOA4 also shares sentences with these, for which no sentence is quoted: papillary carcinoma (7 papers); Hashimoto thyroiditis (4); acute myeloid leukemia (3); anaplastic thyroid carcinoma (2); atherosclerosis (2); colon adenocarcinoma (2); emphysema (2); hemochromatosis (2); Hepatic fibrosis (2); myocardial ischemia (2); acute renal failure (1); acute tubular necrosis (1); adenocarcinoma (1); Airway obstruction (1); brain injury (1); cardiomyopathy (1); cerebral infarction (1); chronic apical periodontitis (1); digestive system cancer (1); endometrial cancer (1); esophageal cancer (1); experimental autoimmune encephalomyelitis (1); follicular adenoma (1); follicular thyroid carcinoma (1); Hearing (1); hematological malignancies (1); Hepatic steatosis (1); immune dysfunction (1); inflammation (1); intraductal carcinoma (1).
A further 32 diseases each share a sentence with NCOA4 in 1 paper.